CMTM6 (CKLF like MARVEL transmembrane domain containing 6)
Diseases named in the same sentence as CMTM6 in open-access papers (continued):
Sharing a sentence is not in itself a finding about the gene and the disease.
cancer (continued). "It has been reported that CMTM6 protects programmed death-ligand-1 (PD-L1) from degradation by targeting it to the PM of cancer cells where it facilitates the immune evasion of cancer, including the immune evasion of CRC17,18." (PMID 39218981, 2024). "CMTM6 is also required for the maintenance of cancer stem cells and TGFβ-induced epithelial-to-mesenchymal transition (EMT) in cancer cells." (PMID 39218981, 2024). "Multiomics revealed that targeting CMTM6 in CRC cells led to global transcriptomic changes in both CRC cells and cancer-associated fibroblasts (CAFs)." (PMID 39218981, 2024). "The uncharacterized protein CMTM6 was shown to be a PD-L-1 regulator on certain cancer cell surfaces using genome-wide CRISPR-Cas9 screening, and further research revealed its regulatory function on the PD-L-1." (PMID 38660299, 2024). "The H-score of the immunohistochemical results showed that CMTM6 expression in cancer tissue was significantly higher than that in adjacent tissues." (PMID 36643629, 2023). "Due to the dominant expression of CMTM6 among the proteins in cancer cells, we next focused on CMTM6 and observed that REIC/Dkk-3 competed with CMTM6 for PD-L1, thereby liberating PD-L1 from its complexation with CMTM6." (PMID 36869893, 2023). "Recent research has shown that HuR can up-regulate CMTM6 expression in a variety of cancers, and this positive correlation was of interest to us." (PMID 37592296, 2023). "Along with the deep-going development of recent research, expression of CMTM6 has been affirmatively related with PD-L1 protein and represents a poor estimated outcome in a variety of cancers." (PMID 37726578, 2023). "Among them, CMTM6 showed relatively high expression in a consistent manner among all the cancer cell lines examined." (PMID 36869893, 2023). "Collectively, these results establish CMTM6 as a regulator of CD58 protein levels in various cancer types and in primary human DCs." (PMID 37683639, 2023). "Next, we analyzed the relationship between CMTM6 and immunoinhibitors in pan-cancer, and showed that CMTM6 was correlated with 24 immunoinhibitors in tumors." (PMID 36698778, 2022). "Chemokine-like factor (CKLF)–like MARVEL transmembrane domain containing 6 (CMTM6) can be observed in various cancers, but its part in OV remains little known." (PMID 35174213, 2022). "In order to have a clearer understanding of the role of CMTM6 expression in tumors, we also analyzed CMTM6 expression in pan-cancer and found that CMTM6 was differentially expressed in a variety of tumors." (PMID 36698778, 2022). "First, we analyzed the relationship of CMTM6 with 45 immunostimulators in pan-cancer at the TISIDB website." (PMID 36698778, 2022). "To evaluate the role of CMTM6 in the OV patient survival, we classified the cancer cases from TCGA cohort into high-expression and low-expression groups." (PMID 35174213, 2022). "To further understand the potential role of CMTM6 in tumors, we further analyzed the expression of CMTM6 in pan-cancer." (PMID 36698778, 2022). "Overall, CMTM6 regulates the Wnt/β-catenin signaling and cancer stemness augmenting chemoresistance in OSCC." (PMID 33434185, 2021). "CKLF like MARVEL transmembrane domain containing 6 (CMTM6) is expressed at the plasma membrane of various cancer cells." (PMID 33757532, 2021). "Presence of CMTM6 led to the activation of the Wnt/β-catenin signaling pathway, which has been implicated in tumorigenesis, EMT, cancer stemness and T cell dysfunction." (PMID 34065396, 2021). "Here we unexpectedly find a strikingly positive correlation between CMTM6 and Hu-Antigen R (HuR) expression in most types of cancer." (PMID 33649535, 2021). "CMTM6 expression data were obtained from The Cancer Genome Atlas (TCGA) for 33 cancer types classified into high and low expression subgroups according to the median CMTM6 expression value." (PMID 33552963, 2020).
cancer (continued). "Recent studies on human cancer cell lines have demonstrated that CKLF-like MARVEL transmembrane domain-containing protein 6 (CMTM6) is a critical regulator of the PD-L1 protein." (PMID 32596272, 2020). "Recent studies identified that CMTM6 was co-localization with PD-L1 and acted as a critical regulator for the maintenance of PD-L1 expression in various cancer types." (PMID 33282744, 2020). "High expression of PD-L1 will promote cancer progression when CMTM6 was overexpressed, but the effect will be reversed when CMTM6 was down-regulated." (PMID 33282744, 2020). "This discovery suggests that, in different types of cancers, the expression of PD-L1 relies on the presence of CMTM6, which is consistent with the previous report in cellular model that PD-L1 relies on CMTM6 to efficiently carry out its inhibitory functions." (PMID 31646201, 2019). "In Summary, we here reported that CMTM6 is expressed in diverse cancers and its expression is correlated with PD-L1 expression." (PMID 31646201, 2019). "CMTM1–8 are known tumor suppressor genes; in addition, CMTM6 is a key regulator of PD-L1 in various human cancer cells." (PMID 31998718, 2019). "The study using immunohistochemistry demonstrated that CMTM6 positivity from 15 out of 19 types of cancers with our in-house tissue microarray, and PD-L1 expression is always found only in CMTM6 positive cancers." (PMID 31646201, 2019). "Pan-cancer analysis of CMTM6 protein expression showed that PD-L1 expression was positively correlated with CMTM6 expression in CCA, implying that high CMTM6 expression could respond better to anti-PD-1/PD-L1 immunotherapy." (PMID 39941920, 2025). "The strategic inhibition of multiple factors—DRG2, TRAPPC4, HIP1R, and CMTM6—represents a compelling approach to regulate PD-L1 surface levels on cancer cells, potentially reversing immune resistance mechanisms and amplifying the effectiveness of PD-1/PD-L1 blockade strategies." (PMID 40507229, 2025). "CMTM6 serves as a crucial regulator of co-stimulatory and co-inhibitory signals in cancer cells." (PMID 39538305, 2024). "The possible biological implications of CMTM6 in cancer have been little explored." (PMID 39335098, 2024). "In many other cancer types, CMTM6 is an indicator of clinical outcome and prognosis." (PMID 38223763, 2024). "A recent study revealed that CMTM6 regulates recycling of PD-L1 in cancer cells and CMTM6 depletion reroutes the internalized PD-L1 to lysosomal degradation of PD-L1, which leads to a decrease in PD-L1 level in cancer cells." (PMID 38802348, 2024). "Since the Warburg effect is a common metabolic feature of cancer cells, understanding the structural basis of the CMTM6/Glut1 interaction may provide opportunities for the design of drugs that target the CMTM6/Glut1 interaction." (PMID 39218981, 2024). "As a result of these transcriptomic changes, CMTM6-knockdown CRC cells exhibited a defect in the G2-to-M phase transition, reduced secretion of 60 cytokines/chemokines, and inability to recruit cancer-associated fibroblasts to support an immunosuppressive CRC liver metastasis microenvironment." (PMID 39218981, 2024). "The majority of previous studies on the role of CMTM6 have focused on how CMTM6 maintains PD-L1 protein levels and targets PD-L1 to the PM, which are processes that are closely related to immune evasion in cancer." (PMID 39218981, 2024). "It has recently been reported that in various cancer cells, the CKLF-like MARVEL transmembrane domain containing 6 (CMTM6) protein is associated with the controlled expression for the programed cell apoptosis 1 ligand 1 (PD-L1) protein by two critically important researches." (PMID 37726578, 2023). "Among the identified receptors, CMTM6 may be especially important in cancer cells since it was expressed at significant levels in cancer cells in a manner consistent with the expression of other receptors." (PMID 36869893, 2023).
cancer (continued). "Recent reports have shown that CMTM6 regulates PD-L1, a key immune checkpoint in numerous cancers." (PMID 35252165, 2022). "We found that cancer-related genes such as Cmtm6 were down-regulated in response to CR." (PMID 34209243, 2021). "The straightforward and stringent regulation of CMTM6 by HuR was demonstrated in our study in ccRCC cells, which might represent a universal mode-of-action in most types of cancer." (PMID 33649535, 2021). "Notably, here we offered the first experimental evidence regarding HuR regulation of CMTM6 expression in cancer." (PMID 33649535, 2021). "Therefore, our data suggested HuR as a positive regulator of CMTM6 in number of human cancers highly likely at transcript level." (PMID 33649535, 2021). "Previous studies have shown that CMTM6 influences the maintenance of cancer stem cells and the EMT." (PMID 34867972, 2021). "Indeed, CMTM6 represents a master regulator of PD-L1 cell surface expression across various cancer types." (PMID 34065396, 2021). "Additionally, association analysis of CMTM6 mRNA levels with Wnt target genes (TCF4, LEF1, CD-44, MMP14, ENC1, ID2, PPARA, and JAG1) from the cancer genome atlas HNSCC cohort using GEPIA showed a positive correlation (r > 0.2)." (PMID 33434185, 2021). "CMTM6 depletion in multiple tissues may decrease PD-L1 expression and cancer incidence through a CR-related mechanism." (PMID 34209243, 2021). "CMTM6 expression is elevated and positively correlated with PD-L1 in cisplatin-resistant cancers." (PMID 33434185, 2021). "There are few studies reporting on CMTM6 expression and prognosis in other cancers." (PMID 32874775, 2020). "We found high heterogeneity in the levels of CMTM6 expression in different cancer types." (PMID 33552963, 2020). "In the immunohistochemical analysis, PD-L1 expression was found in CMTM6- and CMTM4-expresssing cancers, which supports the hypothesis that canine CMTM6 and CMTM4 are involved in the expression of PD-L1." (PMID 32596272, 2020). "CMTM6 expression is significantly related to PD-L1 and may be a useful prognostic indicator and a specific therapeutic target for cancer immunotherapy for GC patients." (PMID 32874775, 2020). "CMTM6 can be used as a key regulator of PD-L1 protein in a broad range of cancer cells." (PMID 33552963, 2020). "To study the regulation of PD-L1 through CMTM6 in clinical samples, we analyzed both PD-L1 and CMTM6 expression in the same set of cancer samples by immunohistochemistry and have demonstrated the expression of CMTM6 and PD-L1 in 15 and 8 out of 19 types of cancers, respectively." (PMID 31646201, 2019). "In addition to interacting with PD-L1, CMTM6 can also enhance Wnt/β-catenin signaling and affect tumorigenesis, cancer stem cell maintenance, and epithelial-to-mesenchymal transition in a variety of cancers." (PMID 38542462, 2024). "Thus, CMTM6 may play a role in the acquisition of cancer stem cell-like properties and in the regulation of EMT through the Wnt/β-catenin pathway, ultimately leading to cisplatin resistance." (PMID 39630300, 2024). "Thus, the role and mechanism of CMTM6 appear to be determined by the specific type of cancer." (PMID 39218981, 2024). "Moreover, in neck squamous cell carcinoma cells, CMTM6 is involved in the maintenance of cancer stem cell (CSC) phenotypes and the induction of epithelial–mesenchymal transition (EMT) by transforming growth factor beta (TGFβ), associated with enhanced Wnt/b-catenin signalling." (PMID 33757532, 2021). "Thus, CMTM6 is a potential target for cancer immunotherapy and effective prognostic biomarker." (PMID 33552963, 2020). "Moreover, we observed that all PD-L1 positive cancers show positivity of CMTM6." (PMID 31646201, 2019). "It has been shown that the number of genetic mutations in patients, the presence of CMTM6 molecules, CD28/B7 status, and intestinal microbes may be associated with new antigens on the surface of cancer cells, PD-L1 half-life, T cell activity, and T cell recruitment, respectively." (PMID 31182061, 2019).
cancer (continued). "Sorting CD58high and CD58low tumor cells revealed that CKLF-like MARVEL Transmembrane Domain Containing 6 (CMTM6) synergistically regulates co-stimulatory (CD58) and co-inhibitory (PD-L1) signals in cancer cells." (PMID 39538305, 2024). "CKLF-like MARVEL transmembrane domain-containing protein 6 (CMTM6) has been identified as a major key regulator of PD-L1, serving as a predicting biomarker for ICI treatment in other carcinomas." (PMID 38542462, 2024). "While this latter link provides only correlative evidence, we note that the frequent concurrent expression of CD58 and CMTM6 in human tumors provides support for the notion that the mechanistic effects here modeled in vitro and in a humanized mouse model may also be at play in human cancer." (PMID 37683639, 2023). "It was reported that CMTM6 and CMTM4 are directly and/or indirectly regulates the expression of PD-L1 in cancer cells and in different immune cells including DCs, macrophages, and monocytes." (PMID 35958549, 2022). "It is suggested that CMTM6 can regulate the activity of Wnt/β-catenin signaling pathway and affect the progression of EMT and the maintenance of cancer stem cells (CSCs) as well as immune response, making it a potential target for HNSCC treatment." (PMID 36698778, 2022). "However, CMTM6 expression and regulation in cancer remain largely unknown." (PMID 33649535, 2021). "The results showed that the expression of TAOK1, CMTM6 and CNOT7 were significantly lower in the adjacent cancers, while the expression of WASF3 was significantly higher in the adjacent cancers." (PMID 34336682, 2021). "Here we unexpectedly uncovered a strikingly positive correlation between CMTM6 and HuR in almost all types of human cancer, and further identified canonical AREs in the 3′UTR region of CMTM6 mRNA." (PMID 33649535, 2021). "Taken together, our data provide the first evidence of CMTM6 and CMTM4 expression in canine cancers and their possible involvement in PD-L1 regulation." (PMID 32596272, 2020). "Recent reports have shown that CMTM6 and CMTM4 are critical regulators of PD-L1 protein expression in human cancer cells." (PMID 32596272, 2020). "To assess the protein expressions of CMTM6 and CMTM4 in canine cancers, we firstly examined the cross-reactivities of commercially available antibodies against human CMTM6 and CMTM4 using canine CMTM6- or CMTM4-expressing cells." (PMID 32596272, 2020). "To elucidate the relationship between CMTM6 expression and diverse infiltrating lymphocytes, we used CIBERSORT to examine the relative fractions of infiltrating immune cell types across 33 cancer types." (PMID 33552963, 2020). "CMTM6 and CMTM4 mRNA expression was detectable in all these samples, suggesting that CMTM6 and CMTM4 are ubiquitously expressed genes in canine immune cells and cancer cells." (PMID 32596272, 2020). "CMTM6 has been identified as a critical PD-L-1 stabilizer in a number of cancer types, such as thyroid, colorectal, pancreatic, and non-small cell lung cancers (NSCLC)." (PMID 38660299, 2024). "Additionally, we evaluated the clinical relevance of CMTM6 and CD58 protein expression in human cancers and explored their potential implications for ICB therapies." (PMID 37683639, 2023). "The expression of CMTM6 and CMTM4 correlated heavily with the prognosis of various cancers." (PMID 35958549, 2022). "In this study, although both PD-L1 and CMTM6 expression was identified in the same cancer samples, their correlation remains obscure due to the limited sample size with no cancers lacking CMTM6 expression." (PMID 32596272, 2020). "PD-L1 expression was present with 12 samples (28.5%) from 8 types of cancers, while negative with the other 11 types of cancers, PD-L1 positive samples are all positive with CMTM6 expression, none of CMTM6 negative samples have positivity for PD-L1 expression." (PMID 31646201, 2019). "CMTM6 positivity was detected with 28 samples (66.7%) from 15 types of cancers, but negative with other 4 types of cancers." (PMID 31646201, 2019).
cancer (continued). "Therefore, CMTM6 and CMTM4 may be attractive to development novel immunotherapeutic stategy for cancer patients with poor outcomes treated by current methods." (PMID 35958549, 2022). "Furthermore, the potential role of TTP in competitively destabilizing CMTM6 needs to be investigated, especially in the cancers lacking correlation between CMTM6 and HuR." (PMID 33649535, 2021). "Furthermore, CMTM6 was shown to drive the formation of the M2a malignant macrophage phenotype, this dual role suggests that CMTM6 promotes oncogenesis by both facilitating TAM recruitment and reprogramming macrophages, making it a promising target for cancer therapy." (PMID 40761779, 2025). "Unlike CMTM6, DRG2 depletion prolonged the localization of PD-L1 at Rab5 early endosomes and increased the total PD-L1 level in cancer cells." (PMID 38802348, 2024).
adenocarcinoma (2 papers, 2023 to 2024). A common cancer characterized by the presence of malignant glandular cells. "Although CRC as an adenocarcinoma is not comparable to HNSCC, this underlies the importance of future studies to elucidate the impact of CMTM6 in solid cancers." (PMID 38067301, 2023).
infection (1 paper, 2010). The state of being infected such as from the introduction of a foreign agent such as serum, vaccine, antigenic substance or organism. "Although Cmtm6 was upregulated similarly in both p38αfl/fl and in VillinCre-p38ΔIEC mice after infection, the expression of most genes in p38αfl/fl mice colon epithelial cells that were upregulated by infection did not change in VillinCre-p38ΔIEC mice colon epithelial cells." (PMID 20532209, 2010).
CMTM6 also shares sentences with these, for which no sentence is quoted: esophageal cancer (4 papers); thyroid cancer (4); lung squamous cell carcinoma (3); ovarian serous cystadenocarcinoma (3); brain glioma (2); rectum adenocarcinoma (2); renal carcinoma (2); uterine carcinosarcoma (2); uterine corpus endometrial carcinoma (2); B cell lymphoma (1); breast invasive carcinoma (1); cervical squamous cell carcinoma (1); cholangiocarcinoma (1); COVID-19 (1); endocervical adenocarcinoma (1); esophageal squamous cell carcinoma (1); gastric tumor (1); lymphoid neoplasm (1); mesothelioma (1); metastatic melanoma (1); neurofibromatosis (1); osteosarcoma (1); ovarian serous adenocarcinoma (1); Pan (1); pheochromocytoma and paraganglioma (1); prostate carcinoma (1); renal adenocarcinoma (1); sarcoma (1); skin cutaneous melanoma (1); thymoma (1).
A further 2 diseases each share a sentence with CMTM6 in 1 paper.